GATA3 (GATA binding protein 3)
Diseases named in the same sentence as GATA3 in open-access papers (continued):
Sharing a sentence is not in itself a finding about the gene and the disease.
lung adenocarcinoma (24 papers, 2013 to 2025). A carcinoma that arises from the lung and is characterized by the presence of malignant glandular epithelial cells. "In lung adenocarcinoma, GATA3 is acetylated at K119 by acetyltransferase CBP and is deacetylated by HDAC1, HDAC2, and HDAC3; GATA3 acetylation inhibits cell migration and invasion, downregulating EMT-related transcription factors SLUG, ZEB1, and ZEB2." (PMID 39275004, 2024). "Some carcinomas, such as colorectal adenocarcinoma, hepatocellular carcinoma, cholangiocarcinoma, gastric adenocarcinoma, lung adenocarcinoma, and papillary and follicular thyroid carcinoma, have less than 10% of GATA3 expression rates." (PMID 37629741, 2023). "Overall, our results clarify that GATA3 has different regulatory effects on NRP1 in two lung adenocarcinoma cells, and H3K4me3 is also involved." (PMID 35993027, 2022). "High GATA3 expression in lung adenocarcinoma has also been considered an evaluation factor of poor prognosis." (PMID 35993027, 2022). "The results showed that the increased GATA3/5 mRNA levels were relevant to better survival probability in lung adenocarcinoma." (PMID 34093794, 2021). "And in Halla's study 15, GATA3 expressed in 2% primary lung adenocarcinoma cases and in 20% primary squamous cell lung carcinoma cases." (PMID 34093794, 2021). "To identify the common targets of FOG2 and GATA3, we performed RNA-sequencing for metastatic lung adenocarcinoma cells expressing shRNAs against FOG2 or GATA319,20." (PMID 30093726, 2018). "While GATA2, 3, and 6 bind to the +220 GATA site, GATA3 is highly expressed in lung and lung adenocarcinoma." (PMID 29299165, 2017). "We previously reported that JAG2, a Notch ligand, promotes lung adenocarcinoma metastasis by suppressing miR-200, which is mediated by GATA3." (PMID 26395571, 2015). "Immunohistochemical analysis is therefore critical to distinguish metastatic breast carcinoma from lung adenocarcinoma; markers such as ER, PR, and GATA3 support a breast origin, whereas TTF-1 and napsin A favor lung adenocarcinoma." (PMID 41426883, 2025). "Of the breast markers, SOX10 has been shown to have the highest sensitivity and specificity (compared to GATA3, MGB and GCDFP-15) to discriminate between TNBC and lung adenocarcinomas to reflect the differential diagnosis of TNBC metastatic to the lung." (PMID 37012444, 2023). "Our analysis of DNA methylation in tumor and normal tissues revealed that KLF9 and GATA3 were significantly higher in tumor tissues compared to normal tissues [Lung squamous cell carcinoma (LUSC), Lung adenocarcinoma (LUAD), Colon adenocarcinoma (COAD), etc.]." (PMID 37000317, 2023). "Here we report that the transcription factor GATA3 and its co-factor FOG2 commonly promote the expression of the lysyl hydroxylase (LH) family members, including LH2 and LH3, which in turn drive lung adenocarcinoma cell migration, invasion, and metastasis." (PMID 30093726, 2018). "Our previous studies have shown that knockdown of GATA3 and its co-factor FOG2 suppresses spontaneous metastasis of 344SQ lung adenocarcinoma cells in syngeneic models of metastasis." (PMID 30093726, 2018). "GATA3 acetylation at K119 mediated by CBP contributes to the inhibition of EMT, indicating that the deacetylation of GATA3 has a promotional effect on EMT in lung adenocarcinoma." (PMID 35484625, 2022). "Hence, other immunostains like GATA3 are used, which is normally negative in lung adenocarcinoma and positive in <10% of the cases." (PMID 40134856, 2025). "Adenocarcinoma of the lung and ductal carcinoma of the breast, which can be differentiated by IHC staining with antibodies of thyroid transcription factor-1 (TTF-1; 75% sensitivity and specificity) and GATA binding protein 3 (GATA-3; over 90% sensitivity and specificity), respectively." (PMID 35433771, 2022). "Furthermore, GATA3 acetylation mediated by acetyltransferase CBP on lysine 119 could inhibit the migration and invasion of lung adenocarcinoma cells." (PMID 34093794, 2021).
lung adenocarcinoma (continued). "In addition, we integrated BMP4 into the JAG/Notch signaling pathway and proposed a regulatory loop consisting of JAG2, GATA3, miR-200, and BMP4, suggesting that BMP4 interconnects with various cell signaling partners to induce tumorigenesis and metastasis in lung adenocarcinomas." (PMID 26395571, 2015). "A core-needle biopsy was performed on the lesion in the left breast, and the pathological examination reported metastasis of lung adenocarcinoma (TTF-1: positive; GATA-3: negative) (Figure A1C,D)." (PMID 40733862, 2023). "In addition, an excision biopsy was performed on the lesion of the right back, and the pathological examination showed metastasis of the lung adenocarcinoma (TTF-1: positive; ALK: negative; GATA-3: negative; CDX-2: negative) (Figure A1E,F)." (PMID 40733862, 2023). "Additionally, the lung mass was histologically similar to the resected urachal carcinoma, with positive expression of CK7, CK20, Villin, and CDX2, and negative for GATA3, TTF1, and NapsinA, supporting the diagnosis of metastatic urachal carcinoma rather than primary lung adenocarcinoma." (PMID 39462217, 2024).
lung carcinoma (24 papers, 2013 to 2025). "Studies have shown that overexpression of GATA3 was found in KRAS-driven lung cancer cells and further promoted tumorigenesis through microRNA." (PMID 37924117, 2023). "Xenograft tumor models were used to evaluate the effect of GATA3 depletion on the tumorigenic behavior of lung cancer cells." (PMID 35993027, 2022). "In lung cancer, miR-200 and GATA binding protein 3 (GATA3), a direct downstream target of Notch involved in lung cancer metastasis, have been shown to mutually inhibit each other." (PMID 26989421, 2016). "With the exception of three CpG sites within GATA3, the distances between other significant CpG sites and their corresponding lung cancer related SNPs were less than 1Mb." (PMID 27323854, 2016). "We identified methylation changes in three genes, VTI1A, STK32A and GATA3 that were rarely reported in relation to lung cancer among Caucasians previously." (PMID 27323854, 2016). "In addition, overexpression of GATA3 was found in KRAS-driven lung cancer cells and further promoted the oncogenesis via microRNAs." (PMID 35936734, 2022). "Therefore, the present study explored the mechanism of GATA3 in two radiation-resistant cell models of nonsmall cell lung cancer (A549-RR and H1299-RR)." (PMID 35993027, 2022). "In addition, intracystic papillary carcinomas are known to rarely metastasize to other organs, and GATA3 staining has been rarely reported in lung carcinomas." (PMID 33542845, 2021). "Taken together, our findings suggest that LHs are pro-metastatic mediators of FOG2 and GATA3 and may be useful candidate therapeutic targets for treating lung cancer." (PMID 30093726, 2018). "Collectively, our data reveal a pro-metastatic GATA3-LHs axis for lung cancer, supporting the notion that targeting LHs may be useful for treating lung cancer." (PMID 30093726, 2018). "Similar to lung cancer cell lines, GATA3 and MEF2D regulate both HDAC9 and BRM." (PMID 24913006, 2014). "However, the molecular mechanism governing GATA3 regulation in lung cancer cells' radiation resistance is unknown." (PMID 35993027, 2022). "The results showed that GATA3 and NRP1, a key gene closely related to the high invasion and metastasis of lung cancer, were highly expressed." (PMID 35993027, 2022). "The currently available literature indicates that exosomal miR-210 is involved in the regulation of various lung cancer-related signaling molecules and pathways, including STAT3, TIMP-1, KRAS/BACH2/GATA-3/RIP3, and PI3K/AKT." (PMID 34440422, 2021). "The most interconnected genes were ESR1, GATA3 (DRG; breast, stomach, prostate, colorectal, lung cancer), and GREB1, all upregulated in ER+ samples, while ERBB2 which was downregulated." (PMID 32605588, 2020). "Like lung cancer, in these Rhabdoid studies, we found that HDAC3, HDAC9, GATA3 and MEF2D regulate BRM." (PMID 24913006, 2014). "Similar to our published studies with lung cancer, we found that BRM was also regulated by HDAC3, HDAC9, GATA3, and MEF2D in Rhabdoid tumors." (PMID 24913006, 2014). "Similar to lung cancer cell lines, we found that HDAC3, HDAC9, MEF2D and GATA3 controlled BRM silencing and that HDAC9 was overexpressed in Rhabdoid cancer cell lines." (PMID 24913006, 2014). "GATA3, an upstream transcriptional regulator of NRP1 gene, regulates the radioresistance of A549 and H1299 cells by opposite mechanisms, which provides a new target for radiotherapy of lung cancer." (PMID 35993027, 2022). "However, the mechanism of action of GATA3 in nonsmall cell lung cancer is still unclear, and whether GATA3 is related to radiation resistance has not been reported." (PMID 35993027, 2022). "E xpression of the hub genes HBEGF, GJA4, DDR1, CD24, TBX2, GATA3, and SASH1 did not appear to be prognostic in lung cancer." (PMID 37324026, 2023).
lung carcinoma (continued). "Lastly, for GATA3 (GATA binding protein 3), no corresponding SNP was disclosed by any GWASs on lung cancer yet, while only an adjacent SNP, rs1663689, was identified in a Chinese population and might mediate genetic damage among workers exposed to polycyclic aromatic hydrocarbons." (PMID 27323854, 2016).
lymphoma (23 papers, 2013 to 2025). A malignant (clonal) proliferation of B- lymphocytes or T- lymphocytes which involves the lymph nodes, bone marrow and/or extranodal sites. "While long-term survivors were rarely observed among GATA-3 deficient lymphomas, preserved GATA-3 expression was uniformly fatal, and chemotherapy administration associated with a clinically insignificant prolongation in survival." (PMID 36329027, 2022). "The observation that a PTCL, NOS subset highly expressed GATA-3, particularly in view of its long established role in Th2 cell differentiation, was ontologically interpreted, associating GATA-3 expression with a Th2 “cell of origin” in these lymphomas." (PMID 36329027, 2022). "Substantial efforts have been made to find a good immunohistochemical marker of the mediastinal lymphomas, and recently, p63, cyclin E and GATA3 have emerged as new diagnostic markers." (PMID 31831043, 2019). "T-cell receptor signaling plays an important role in upregulating GATA-3 protein expression in both conventional and malignant T cells in a PI3K/AKT dependent manner, suggesting that PTEN loss may promote translation of GATA-3 transcripts in these lymphomas." (PMID 36845711, 2023). "Inherited genetic variation in GATA3 has been associated with lymphoma susceptibility." (PMID 27588406, 2016). "Comparing the staining results, the TBX21 subtype is more common in AITL and other TFH lymphomas than the GATA3 subtype." (PMID 33990228, 2021). "Some typical biomarkers of lymphoma were included, such as the five miRNA biomarkers (miR-150, miR-21, miR-155, miR-17, and miR-146a) for distinguishing lymphoma from reactive lymphoid hyperplasia and the T-cell lineage protein GATA3." (PMID 33193722, 2020). "The median lymphoma-free survival time was 20 months in p18−/−;Gata3+/− mice and the earliest lymphomas were detected at 8 months of age." (PMID 27588406, 2016). "We determined the expression of transcription factors related with T and B cell differentiation in four representative p18−/−;Gata3+/− lymphomas." (PMID 27588406, 2016). "Together, these results demonstrate that p18−/−;Gata3+/− lymphoma cells are transplantable and highly tumorigenic into secondary immunodeficient mice." (PMID 27588406, 2016). "Histological analysis revealed that some p18−/−;Gata3+/− mice displayed typical lymphoma pathology, such as effacement of normal architecture and uniform cell morphology." (PMID 27588406, 2016). "We then performed FACS and IHC and found that in lymphoma-free mice at older ages (14–16 months), B220+ cells from p18−/−;Gata3+/− spleens incorporated more BrdU and had a higher percentage of Ki67+ cells than those from age-matched p18−/− cells." (PMID 27588406, 2016). "We performed immunohistochemistry (IHC) and immunofluorescence analysis for p18−/−; Gata3+/− lymphomas and found that the majority of lymphoma cells were B220+ and a small portion of the cells were CD3+." (PMID 27588406, 2016). "Further, the percentages of BrdU+ or Ki67+ B cells from p18−/−; Gata3+/− lymphomas were significantly more than cells from lymphoma-free spleens of the same genotype." (PMID 27588406, 2016). "p18−/−;Gata3+/− spleens and lymph nodes with lymphomas exhibited aberrant B220+IgM− or B220+IgM+ cell populations relative to age-matched tumor-free counterparts of the same genotype." (PMID 27588406, 2016).
lymphoma (continued). "We then transplanted two million cells isolated from a p18−/−;Gata3+/− splenic lymphoma (immature B-cell lymphoma) or an asymptomatic spleen into each female NSG mouse (n = 3 for each group) by tail vein injection." (PMID 27588406, 2016). "Conversely, expression of GATA3, a key T-cell developmental gene silenced in aggressive lymphoma cells, was partially restored by PCM1-JAK2 knockdown." (PMID 23372669, 2013). "Instead, the PTCL that emerged in transgenic mice highly expressed GATA-3 and transcriptionally resembled GATA-3 associated PTCL, NOS, and resembling their human counterparts, marked c-Myc pathway activation was also observed in these lymphomas." (PMID 36845711, 2023). "In summary, GATA-3 induces transcriptional programs that promote cell growth and proliferation, and is thus a bona fide proto-oncogene in various T-cell neoplasms across the continuum of immature to mature T-cell leukemias/lymphomas." (PMID 36329027, 2022). "In addition, some of the mature lymphomas exhibit GATA3+ TH2 subtype molecular features although, in most cases, are negative for CD4." (PMID 35895495, 2022). "While the GATA-3 dependent transcriptional programs we identified would suggest that GATA-3 directly regulates the biology of these lymphomas, the genetic landscape of these lymphomas undoubtedly contributes to their aggressive natural history and poor responses to existing therapies." (PMID 36329027, 2022). "AITL and other TFH lymphomas showed the TBX21 subtype more commonly than the GATA3 subtype." (PMID 33990228, 2021). "We performed loss of heterozygosity (LOH) analysis for p18−/−;Gata3+/− lymphomas and found that the remaining WT allele of Gata3 is absent in at least 2 out of 5 tumors examined, further supporting the role of Gata3 in suppressing B cell lymphomas." (PMID 27588406, 2016). "In addition, GATA3 appears to promote carcinogenesis in a lymphoma model induced by the increased expression of c-Myc, which in turn induces Notch1 and GATA3 as putative transcriptional targets that cooperate with Myc to establish a malignant phenotype." (PMID 24205108, 2013). "Upon adoptive transfer, prolonged survival was observed in GATA-3 deficient lymphomas whether or not recipient mice were treated with cyclophosphamide and vincristine." (PMID 36329027, 2022). "Collectively, our findings do not support the hypothesis that GATA-3 is merely a surrogate marker for a genetically high-risk group of lymphomas." (PMID 36329027, 2022). "In addition, T lymphoma cells may promote the differentiation of M2-type macrophages through a GATA3-dependent mechanism." (PMID 27589565, 2016). "In addition, GATA-3 dependent cytokines have important non-cell-autonomous roles, including promoting the expansion and polarization of lymphoma-associated macrophages, which are a dependency, and associated with poor outcomes, in these lymphomas." (PMID 41309546, 2025). "However, a comprehensive and systematic analysis of GATA-3 target genes in malignant T cells demonstrated that GATA-3 targets (e.g. including c-myc) are oncogenic, and further demonstrated via loss-of-function and gain-of-function studies that GATA-3 is a bona fide proto-oncogene in these lymphomas." (PMID 36845711, 2023). "When examining large B-cell lymphomas, GATA3 was found to be positively expressed in 80% of CHL, 75% in PMBL, and 100% in gray zone lymphomas (GZLs)." (PMID 38179383, 2023). "The overexpression of GATA3 in T cells during development in thymic lymphoma directs DP cells towards CD4 lineage, enhances lymphoma development, and increases thymocytes size in CD2-Gata3 transgenic mice." (PMID 35681778, 2022).
lymphoma (continued). "However, in conventional (non-malignant) T cells, GATA-3’s role is not limited to T-cell differentiation, as GATA-3 also regulates cell growth and proliferation, thus suggesting that GATA-3 may have a previously uncharacterized oncogenic role in these lymphomas." (PMID 36329027, 2022). "In other TFH lymphomas (N = 11), the TBX21 subtype (N = 10/11, 90.9%) was more common than the GATA3 subtype (N = 1/11, 9.1%)." (PMID 33990228, 2021). "Heterozygous germline deletion of Gata3 alone does not result in lymphoma development, though aberrantly differentiated B cells proliferate slightly faster than WT B cells at early ages, indicating that haploid loss of Gata3 is not sufficient to induce lymphomas." (PMID 27588406, 2016). "We found that all lymphomas exhibited the same clonal rearrangement (DHJ4 0.12kb), indicating that the lymphomas developed from p18−/−;Gata3+/− mice were clonal." (PMID 27588406, 2016). "GATA binding protein 3 (GATA-3) is another marker which may represent a potential source of misdiagnosis between carcinoma and lymphoma." (PMID 35200580, 2022). "About 1/3 (5 of 14) p18−/−;Gata3+/− lymphomas infiltrated into non-lymphoid organs including the liver, kidney, or lung." (PMID 27588406, 2016). "Furthermore, our observation that selected GATA-3 target genes, including c-Myc, CCR4, IKZF3 and ITK, are therapeutically targetable is noteworthy, as improved therapeutic strategies for these lymphomas are clearly needed." (PMID 36329027, 2022). "Due to the very low level of GATA3 expression in B cells that is undetectable by western blot and IHC (Pei unpublished data), we were unable to determine whether Gata3 expression is further reduced in tumor cells of p18−/−;Gata3+/−lymphomas with LOH relative to lymphoma-free B cells." (PMID 27588406, 2016). "In addition, these cells had higher levels of the transcription factor Hes1 suggesting that NOTCH signalling might play a role in malignant transformation in GATA3-overexpressing cells, presumably via c-MYC, which is a direct target of NOTCH1 in T lymphoblastic leukaemia/lymphoma." (PMID 35681778, 2022).